ROS1 (ROS proto-oncogene 1, receptor tyrosine kinase)
Diseases named in the same sentence as ROS1 in open-access papers (continued):
Sharing a sentence is not in itself a finding about the gene and the disease.
tumor (continued). "APG-2449, a TKI targeting ALK, ROS1, and focal adhesion kinase (FAK), has shown anti-tumor activity in preclinical models and is currently being tested in a phase I dose escalation and expansion trial that enrolled patients with ALK/ROS1 positive NSCLC." (PMID 39199633, 2024). "ROS1 is highly similar to ALK with regard to biochemical properties and the spectrum of tumor types carrying actionable rearrangements, although its alterations are detected at significantly lower frequencies." (PMID 38612902, 2024). "Further, in specimens with low DNA yield and <30% tumor content sequenced by TSO500, tier 1 fusion genes were detected in ROS1 (also reported by SOC) and RET." (PMID 38398180, 2024). "Moreover, the presence of additional mutations that might explain the tumor evolution, such as tumor-suppressor inactivating variants or copy number gains of oncogenes, has not been fully characterized within the ROS1+ NSCLC setting." (PMID 39737401, 2024). "Here TSO500 detected a ROS1 fusion and EGFR: p.Leu861Gln in two cases, with 12% and 29% tumor content, respectively." (PMID 38398180, 2024). "Three out of the four ROS1-rearranged tumor subtypes were included in the analysis, as there were at least two independent samples per fusion type (CD74-ROS1, SLC34A2-ROS1, and EZR-ROS1)." (PMID 39737401, 2024). "These cumulative findings indicated that targeting ROS1 with either crizotinib or entrectinib, in conjunction with IN10018-mediated FAK inhibition, enhanced the in vivo anti-tumor effects of either monotherapy in both CDX and PDX CDH1-deficient mouse models." (PMID 37324948, 2023). "The right panel shows a combination therapy of ROS1 and AXL inhibitors blocks AKT signaling, thus leading to tumor cell death." (PMID 37727007, 2023). "In this study, we showed that HGF, which can be produced by fibroblasts in the tumor microenvironment, induces entrectinib resistance by activating its receptor MET and downstream signaling pathways in NTRK1‐rearranged or ROS1‐rearranged tumor cells." (PMID 36416133, 2023). "With the exception of NTRK and RET fusions, all of the US FDA approvals are tumor-specific: ALK (non-small cell lung cancer [NSCLC]), ROS1 (NSCLC), and FGFR2-3 (urothelial, cholangiocarcinoma)." (PMID 37853341, 2023). "We found that the minimum amount of RNA needed for the detection of ALK, ROS1, RET fusion transcripts, and METΔex14 ranged between 1 and 10 pg·μL−1, corresponding to 0.1–0.01% fraction of tumor RNA." (PMID 37243883, 2023). "For those low-quality and very limited samples, in situ approaches such as ALK IHC and ALK/ROS1/RET/NTRK FISH, which can also evaluate a small number of tumor cells, can be useful options." (PMID 37190044, 2023). "Patients who carried driver gene mutations (EGFR or BRAF mutations or ALK/ROS1 rearrangements), who received ICIs as neoadjuvant treatment or less than two cycles of ICIs, who were lost to follow-up, and who did not complete the tumor response assessment were excluded from the study." (PMID 37359565, 2023). "Using cell lines harboring various targetable kinase gene fusions, the limit of detection was determined to be 10% tumor cell content for ALK, ROS1, and RET rearrangements." (PMID 37628603, 2023). "ROS1 FISH is still useful for validation of the diagnosis in the case of uncertain NGS results and/or of very small tissue biopsies with a few tumor cells." (PMID 37240980, 2023). "Inhibits will disrupt the ALK and ROS1- mediated signaling, further inhibiting the growing tumor cells in ALK and ROS1 cells." (PMID 37259442, 2023). "At present, probes able to search simultaneously for ALK and ROS-1 rearrangements, such as Vysis ALK/ROS-1 Dual Break Apart Probe Kit (RUO)) or FlexISH ALK/ROS-1 DistinguISH Probe Zytvision, require less tumor material and can be run on cytological samples." (PMID 35200557, 2022).
tumor (continued). "In advanced tumor stages, ACA showed ROS1 fusions in 0.6% (4/650) of cases: two patients with EZR-ROS1, one patient with SDC 4–ROS1, and one patient with CD74–ROS1 fusion." (PMID 36293366, 2022). "The AcSé program in France supported a multi-tumor phase II trial wherein 107 pediatric tumors were analyzed for alterations in the molecular targets of crizotinib (ALK, MET, and ROS-1)." (PMID 36034555, 2022). "In another study, tumor-specific alterations in ROS1 were identified by proprietary Guardant360® NGS technology, utilizing plasma from patients with ROS1-positive NSCLC." (PMID 36012272, 2022). "The observations from our study should be validated in larger studies in patients with a de novo diagnosis of metastatic ROS1‐ and ALK‐rearranged NSCLCs to control for lead time bias and for more comprehensive tumor molecular typing." (PMID 35510711, 2022). "They described the case report of an ALK-RCC patient who relapsed after complete resection of the tumor and, therefore, received first-line treatment with entrectinib, a selective TKI towards neurotrophic tyrosine receptor kinase (NTRK), ROS1, and ALK fusion." (PMID 35409355, 2022). "Though ALK and ROS1 fusion proteins existed in multiple tumor types, ALK and ROS1 kinases inhibitors are only approved for ALK or ROS1‐positive NSCLC before July 14, 2022." (PMID 36254250, 2022). "The current mandatory biomarkers to look for in late-stage NS-NSCLC include different genomic alterations present on EGFR, ALK, ROS1, NTRK, BRAF, MET, and RET, as well as the PD-L1 expression of tumor cells." (PMID 35565387, 2022). "Immunohistochemistry testing also identified 49 patients (4.1%) with tumor ALK fusions among 1202 patients who underwent testing, and 16 patients (1.1%) had ROS1 rearrangements confirmed by FISH." (PMID 35877212, 2022). "With an in-depth study of the biological mechanism of tumor cells, the status of target genes in gene targeting therapy, such as EGFR, MET, and ROS1, has gradually become prominent." (PMID 36589752, 2022). "In contrast, mutant BRAF, ATM, LRP1B, FAT4, FMN2, TRRAP, and ROS1 had higher stromal score (except ATM), immune score and ESTIMATE score, and the tumor purity was lower than the wild-type." (PMID 33836681, 2021). "In contrast, ROS1 fusion only accounted for a small fraction of patients in NSCLC (<2% in both datasets), and even rare in other tumor types." (PMID 34221982, 2021). "ROS1 fusions have been identified on NSLCL line HCC78 (SLC34A2-ROS1) and on tumor sample (CD74-ROS1), leading to constitutive kinase activation and conferring sensitivity in vitro to TKIs." (PMID 34884672, 2021). "In these 76 patients, genomic profiling of 128 tumors by MSK-IMPACT yielded a median of 8 somatic alterations per tumor (range, 1–47), and a major oncogenic driver alteration (e.g., EGFR, KRAS, ALK, ROS1, or MET exon 14) was identified in 107 tumors (84%)." (PMID 34359558, 2021). "Druggable fusion events were identified in 7.1% (5/70) of tumor specimens: FGFR3-TACC3 (n = 2), NTRK2 fusions (n = 1), ALK (n = 1), and ROS1 (n = 1)." (PMID 34234122, 2021). "This includes tumor gene sequencing as well as the use of specific targeted drugs for tumors with targetable alterations (e.g., EGFR, ALK, ROS1, NTRK, BRAF, or HER inhibitors)." (PMID 34070597, 2021). "The kinase inhibition leads to disruption of ALK- and ROS1-mediated signaling and eventually inhibits tumor cell growth in ALK- and ROS1-overexpressing tumor cells." (PMID 34443583, 2021). "Among the genes upregulated in the atypical tumor compared to the nevus were: SOX10, the receptor tyrosine kinases ROS1 and NTRK3, PLA2G2A, and HOXA11, while DUSP2, PDGFD, and ELN were downregulated." (PMID 35052351, 2021). "We have shown that recovered CTCs from selected patients with ROS1, ALK, and RET rearrangements carried genomic aberrations matching the primary tumor." (PMID 31947893, 2020).
tumor (continued). "Crizotinib is believed to exhibit antitumor effects by inhibiting the kinases ALK, ROS1, and c-MET and suppressing the activation of these factors, tumor cell proliferation, and tumor angiogenesis." (PMID 32882995, 2020). "Among four patients, one experienced relapse; the tumor harbored a SNV in NF1 (Arg1362*) and ROS1-GOPC fusion." (PMID 32493317, 2020). "ROS1 and RASAL1 are two genes with established roles in tumor development and progression in different types of cancer." (PMID 32906649, 2020). "Currently, tumor genotyping is critical as personalized treatment for EGFR, ALK, ROS1, BRAF in the first-line setting." (PMID 32525942, 2020). "ROS1, a tyrosine kinase receptor endowed with oncoantigen features, is activated by chromosomal rearrangement or overexpression in NSCLC and in several tumor histotypes." (PMID 32268572, 2020). "Since immunotherapy can be proposed alone or in combination with first-line chemotherapy in patients whose tumors are wild type for EGFR, ALK, ROS1, and BRAF, it is obligatory to obtain the PD-L1 status of tumor cells." (PMID 32294880, 2020). "Fusion partners that participate in ROS1 rearrangements include CD74, SLC34A2, SDC4 in addition to GOPC/FIG, which was observed in this patient's tumor." (PMID 30719217, 2019). "All tumors were analyzed using an NGS multi-gene panel that expands the tumor genetic portrait, including genes such as BRAF, ERBB2, KRAS, and MET in addition to EGFR and ALK/ROS1, in accordance with recently updated recommendations." (PMID 30669267, 2019). "Forty-four unique fusions were identified in 40 (1.1%) of the 3,808 patients with circulating tumor DNA detected: RET (n = 6; 36% of all fusions detected), FGFR3 (n = 2; 27%), ALK (n = 10, 23%), NTRK1 (n = 3; 7%), ROS1 (n = 2; 5%), and FGFR2 (n = 1; 2%)." (PMID 33015522, 2019). "Additional tumor material is required for interrogating predictive biomarkers, using IHC (e.g., ALK, ROS1, PD-L1), in situ hybridization (ISH; e.g., ALK, ROS1) or sequencing techniques (e.g., EGFR, BRAF V600E, etc.)." (PMID 30818873, 2019). "Although the tumor histology varied widely in this study, the median progression-free survival for patients harboring rearrangements in NTRK1/2/3, ROS1, and ALK is 19.0 months." (PMID 29617282, 2018). "CCDC6 has been involved in different rearrangements with several tyrosine kinases (RET, PDGFRb, ROS1, FGFR2) in several tumours (thyroid, lung, leukemia, breast, iCCA)." (PMID 29455670, 2018). "The high homology between ROS1 and ALK renders ROS1-rearranged tumours sensitive to several ALK inhibitors." (PMID 29225694, 2017). "The tumor response was evaluated in 15 patients who received oral crizotinib with advanced NSCLC and ROS1 fusion-positive." (PMID 27738334, 2016). "For the transcriptomic analysis, we compared maize tumor tissue infected by strains FB1 x FB2 and the corresponding ros1 deletion strains." (PMID 27332891, 2016). "Tumour specimens with known ROS1 rearrangement, or a cellblock of the HCC78 cell line harbouring the SLC34A2-ROS1 fusion gene, can serve as positive controls." (PMID 27535289, 2016). "Globular ROS1 immunoreactivity has been described in tumour specimens with the CD74-ROS1 fusion, and membranous staining has been observed in tumours with the EZR-ROS1 fusion." (PMID 27535289, 2016). "One ADC tumor was positive for both EGFR and c-Met, and two tumors were positive for both c-Met and ROS1." (PMID 25989941, 2015). "This was accomplished using tumor samples from a NSCLC patient who became resistant to crizotinib and a NSCLC cell line that we made resistant to ROS1 inhibition by continuous culture in the ROS1 inhibitor TAE684." (PMID 24349229, 2013). "Through next-generation sequencing (NGS) analysis of circulating tumor DNA (ctDNA) and tumor tissue DNA (ttDNA) from these patients, mutations in PBRM1, SETD2, and ROS1 were frequently detected in both ctDNA and ttDNA of non-responders." (PMID 41602395, 2026).
tumor (continued). "In the classification map for the ROS1 fusion negative case, several non-tumor areas are incorrectly marked with a higher likelihood of ROS1 fusion positivity (shown in darker red)." (PMID 40739404, 2025). "ROS1 alterations, particularly gene fusions, are pivotal in oncogenesis by activating RAS-RAF-MEK-ERK, PI3K-AKT-mTOR, and JAK-STAT3 signaling pathways, driving tumor cell proliferation and survival." (PMID 40576713, 2025). "In another large cohort, 100 of 1173 (8.53%) NSCLC patients’ tumor were identified as RDAA positive that does not have known and targetable EGFR/ALK/ROS1 mutation or rearrangement." (PMID 40246819, 2025). "For 4 out of 31 patients, no ROS1 fusion was detected, despite having a tumor cell percentage > 20%." (PMID 40878657, 2025). "The ROS1 translocation had not been present upon the initial diagnosis, which has been confirmed by a recently performed post hoc test using the tumour cells obtained at the time of the first diagnosis." (PMID 38891886, 2024). "We identified FGFR2::BICC1 fusions in two tumours, and FGFR2::KCTD1 and TMEM106B::ROS1 as novel fusions with potential therapeutic implications in iCCA and confirmed oncogenic properties of TMEM106B::ROS1 in vitro." (PMID 38877653, 2024). "Importantly, the main limitation of this study is the low sample size of ROS1-, ALK- and RET-rearranged tumors, which is explained by the low prevalence of each tumor subtype." (PMID 39737401, 2024). "Besides its role in tumorigenesis, the Hippo pathway plays a pivotal role in drug resistance of NSCLC via crosstalk with other well-known tumor-promoting factors such as EGFR, ALK, BRAF, KRAS, and ROS1." (PMID 38499647, 2024). "Our study showed that PD-L1 expression was not affected by age, sex, histopathological type, tumor stage, or ROS1 fusion subtypes." (PMID 38835380, 2024). "The molecular testing (Oncomine Focus Assay) of the tumour cells from the pleural effusion showed persistent EGFR p.L858R and HER2 p.S310F mutations, but no ROS1 fusion transcripts." (PMID 38891886, 2024). "Our findings suggest that growth factors in the tumor microenvironment, such as HGF, may induce resistance to entrectinib in tumors with NTRK1 or ROS1 rearrangements." (PMID 36416133, 2023). "While ROS1+ NSCLC tumors were the dominant tumor type at 78.8% and has US FDA approved treatment of two ROS1 TKIs, it implies that potentially more than 20% of the ROS1+ solid tumor may benefit from currently approved ROS1 TKIs." (PMID 37853341, 2023). "Despite the protein overexpression of MET, in the absence of additional genomic alterations in MET, tumor cells were ROS1-dependent, as evidenced by the initial durable responses to ROS1 inhibitors crizotinib (14 months) and then lorlatinib (30 months)." (PMID 37923925, 2023). "These tumours also had similar detection rates for EGFR mutations and for RET, ROS1, ALK and MET oncogenic isoforms compared with tumours in never-smokers, which suggests that they have a similar aetiology and pathogenesis." (PMID 37046096, 2023). "Fourthly, tumor mutation-driver genes such as EGFR, ALK, and ROS1 and the use of targeted therapies were not recorded in the SEER data, and reflecting the time period of this study, neither were tumor PDL-1 status and the use of immunotherapy." (PMID 35847910, 2022). "Recent discoveries pointed out that these neoplasms, with a clinical course that differs from their pediatric and adult counterparts, carry specific molecular alterations, namely kinase (ALK, NTRK1/2/3, ROS1, or MET) gene fusions." (PMID 35565372, 2022). "Moreover, the simultaneous analysis of RNA extracted from the same samples allowed not only for the screening of fusion genes in specific tumor types (e.g., ALK and ROS1 fusions in NSCLC) but also in a tumor type agnostic setting (e.g., NTRK fusions)." (PMID 35626061, 2022).
tumor (continued). "Tumor driver genes in NSCLC patients have been uncovered one by one, including epidermal growth factor receptor (EGFR), mesenchymal lymphoma kinase (ALK), and receptor tyrosine kinase ROS proto-oncogene 1 (ROS1) mutants." (PMID 36499382, 2022). "There was a significant difference in sum of the longest diameters between tumours where ROS1 was detected compared with those where no ROS1 fusion was detected; this was not the case for NTRK fusions." (PMID 35338679, 2022). "The European Organization for Research and Treatment of Cancer (EORTC) “CREATE” trial was designed as a multi-center multi-tumor trial to evaluate crizotinib in a range of cancer types known to harbor alterations in the targets of crizotinib (ALK, MET, and ROS-1)." (PMID 36034555, 2022). "In a clinical study of 25 patients who had various malignancies containing NTRK, ROS1, or ALK gene fuses and received an effective dose of entrectinib, an overall response rate of 79% with significant tumor regression in all NTRK-altered tumors (including ETv6: NTRK3 translocation) was observed." (PMID 35190738, 2022). "Several targeted therapies have been approved for the treatment of NSCLC harboring certain genetic variations in EGFR, ALK, ROS1, or BRAF and it is required to determine the existence of those genetic variations in tumor before targeted therapies are given to patients." (PMID 35061839, 2022). "In the era of molecularly driven therapies, offering sequential targeted treatment options in ALK and ROS1-positive NSCLC, re-characterization of the tumor via repeated biopsies has become an established procedure and was carried out in 50% of patients in the routine setting." (PMID 33613692, 2021). "Four tumor samples with confirmed fusions from clinical variant analysis, three in ALK and one in ROS1, were further analyzed with AVENIO FFPE, where neither of the fusions were detected." (PMID 34217228, 2021). "Since the amino acid sequence of the kinase domains of ROS1 and ALK are highly homologous, selective inhibitors of ALK, including crizotinib, have shown anti-tumor activity in vitro and have been explored clinically in the treatment of patients with ROS1-rearranged tumors." (PMID 34511132, 2021). "These three “double-positive” patients became all FISH positive at tumor re-biopsy; the two EGFR/ROS1 patients had been treated with EGFR-TKIs, and the confirmed FISH positivity at tumor re-biopsy seems to suggest an expansion of the ROS1-positive clone under EGFR target therapy pressure." (PMID 34884672, 2021). "Immunoreactivity for ALK and ROS1 resulted negative in both component, in primitive tumor and in lymph nodal metastasis." (PMID 34926584, 2021). "No immunoreactivity for ALK and ROS1 with PD-L1 TPS of >50% were documented in the lower lobe neoplasia." (PMID 34926584, 2021). "By immunohistochemistry, tumor cells demonstrated strong nuclear cyclin D1 expression and multifocal smooth muscle actin staining but were negative for MUC4, ERG, CD34, S-100 protein, desmin, STAT6, CD45, MDM2, CDK4, ALK, and ROS1." (PMID 32461620, 2020). "In general, squamous patients with NSCLC bear a heavier tumor mutational burden with exception of targetable genomic mutations (e.g., EGFR, KRAS, or ROS1) than nonsquamous patients with NSCLC." (PMID 31693178, 2020). "Since oncogenic driver alterations may modulate immune response in tumor microenvironment that may influence prognosis in LUAD, the effects of EGFR, ALK, ROS1, and BRAF alterations on tumor microenvironment remain unclear." (PMID 33585210, 2020). "However, some actionable targets can be present in other genes (notably MET, RET, NTRK, and HER2), allowing inclusion into clinical trials of patients with EGFR, ALK, ROS1, and BRAF wild-type tumors with less than 50% PD-L1-positive tumor cells." (PMID 32294880, 2020).